STX1B (syntaxin 1B)
Diseases named in the same sentence as STX1B in open-access papers (continued):
Sharing a sentence is not in itself a finding about the gene and the disease.
cancer (3 papers, 2021 to 2024). A tumor composed of atypical neoplastic, often pleomorphic cells that invade other tissues. "In particular, Shiga toxin 1 B-subunit (Stx1B) has been coupled to several chemotherapeutic compounds for targeting tumors, with excellent outcomes in intracellular transport of such drugs and elimination of cancer cells." (PMID 36494671, 2022). "The Stx1B-scFv OKT3 lectibody could redirect unstimulated peripheral T cells to lyse Gb3+ Ramos cancer cells in a concentration-dependent fashion." (PMID 36494671, 2022). "Affinities in the nanomolar range have been observed between Stx1B and cancer cells." (PMID 33499141, 2021). "The binding of Stx1B-displaying L. lactis to cancer cells was analyzed." (PMID 33499141, 2021). "Overall, both Stx1B- and CNL-displaying L. lactis showed a weak to moderate level of adhesion to HT-29 and Caco-2 cancer cells in comparison to the high level of adhesion of Stx1B-displaying L. lactis to HeLa cells." (PMID 33499141, 2021). "In this study, two lectins, the B subunit of Shiga holotoxin (Stx1B) and Clitocybe nebularis lectin (CNL), have been applied to target L. lactis to cancer cells." (PMID 33499141, 2021). "After verifying the presence of lectins’ target sites on HeLa, HT-29 and Caco-2 cells, we displayed Stx1B and CNL, individually, on the surface of L. lactis and assessed the adhesion of engineered bacteria on target cancer cells." (PMID 33499141, 2021). "Finally, we evaluated the binding of engineered Stx1B and CNL lectin-displaying L. lactis to cancer cells." (PMID 33499141, 2021).
neurological disease (2 papers, 2024 to 2025). "Interestingly, SETD1A and the STX1B distal target are both associated with neurological disorders, while the HSD3DB7 and STX4 distal targets are associated with immune-related and cardiometabolic diseases, respectively." (PMID 39727170, 2025).
infection (1 paper, 2014). The state of being infected such as from the introduction of a foreign agent such as serum, vaccine, antigenic substance or organism. "Intranasal immunization with Stx2B-Tir-Stx1B-Zot protein led to less shedding in goats after experimental infection with E. coli O157:H7." (PMID 24632795, 2014).
tumor (1 paper, 2022). "Interestingly, in addition to Stx1B, several other bacterial lectins have found application in tumor detection or treatment." (PMID 36494671, 2022). "As a next step, we examined the binding of conjugated Stx1B-scFv OKT3 to tumor and effector cells." (PMID 36494671, 2022). "Additionally, a comparative analysis of the Stx1B wild-type and the Stx1B K9AzK mutant expressed in this study confirmed the specificity of the AzK mutant towards Gb3 on the surface of these tumor cells." (PMID 36494671, 2022). "Therefore, our study aimed to show that a bispecific lectibody with the lectin Stx1B as tumor-targeting domain and scFv OKT3 as a T cell engager could redirect T lymphocytes’ cytotoxicity towards Gb3-expressing tumor cells." (PMID 36494671, 2022). "Lower concentrations of Stx1B-scFv OKT3 (7 nM) induced around 40% of tumor cell lysis at 24 h, followed by an increase in tumor cell death to about 70% at 48 h." (PMID 36494671, 2022). "While the treatment with a lower dose (7 nM) induced a maximum of 52% of tumor cell killing after 72 h, target cells treated with 35.6 nM Stx1B-scFv OKT3 displayed 81% of lysis at 48 h, culminating in 90% of tumor cell elimination at 72 h post-treatment." (PMID 36494671, 2022). "In vitro cell-based assays revealed that the Stx1B-scFv OKT3 lectibody can simultaneously engage CTLs and Gb3+ tumor cells, redirecting T cell cytotoxicity in a highly selective manner and resulting in nearly complete tumor cell lysis." (PMID 36494671, 2022). "The induction of CD25 expression on T cells was relevant when they were stimulated with Stx1B-scFv OKT3, but only in the presence of Gb3+ tumor cells." (PMID 36494671, 2022). "A combinatorial strategy of this type could increase Stx1B-scFv OKT3 efficacy by enhancing and maintaining T cell activity for tumor eradication." (PMID 36494671, 2022). "Although the mechanism of action of Stx1B-scFv OKT3 has to be further explored in vivo, we demonstrate encouraging properties of a bispecific lectin-based platform that selectively targets altered glycostructures on tumor cells." (PMID 36494671, 2022).
STX1B also shares sentences with these, for which no sentence is quoted: Ataxia (3 papers); Doose syndrome (3); developmental delay (2); movement disorder (2); neurodevelopmental disorder (2); Obesity (2); West syndrome (2); autism spectrum disorder (1); behavioral disorders (1); cerebellar ataxia (1); Chorea (1); depression (1); developmental and epileptic encephalopathy (1); Dystonia (1); epileptic encephalopathies (1); febrile seizures (1); Fever (1); genetic generalized epilepsies (1); glioblastoma (1); Hypoalbuminemia (1); Intellectual disability (1); Lennox-Gastaut syndrome (1); myoclonic epilepsy (1); neurodegenerative disease (1); Neurodevelopmental delay (1); Ohtahara syndrome (1); pancreatic cancer (1); periodontitis (1); prion disease (1); Rett-like syndrome (1).
A further 1 disease shares a sentence with STX1B in 1 paper.